S100A8 (S100 calcium binding protein A8)
Diseases named in the same sentence as S100A8 in open-access papers (continued):
Sharing a sentence is not in itself a finding about the gene and the disease.
tumor (continued). "S100A8 forms heterocomplexes with S100A9.34, 35 Downregulation of either S100A8 or S100A9 in cancer cells reduced tumor migration and invasion." (PMID 27086923, 2016). "Neutrophils accumulating in pre-metastatic lungs support tumor cell extravasation and proliferation by release of pro-metastatic proteins, e.g., Bv8, MMP9, S100A8, and S100A9." (PMID 28066438, 2016). "Reduction in MMP2 and MMP9 expression after S100A8 and S100A9 knockdown in the cancer cells suggests their regulation by the S100 proteins, and is consistent with decreased tumor cell migration and invasion." (PMID 27086923, 2016). "We next determined the levels of protein expression for several examples by flow cytometry of non-separated ascites samples and confirmed the preferential expression of S100A8/A9 and IL-8 in TAMs, and of LIFR and TGFBR3 in tumor cells." (PMID 27215396, 2016). "Our results correlate with other published data, where a relation between tumor growth and RAGE/S100A8/A9 axis was reported." (PMID 25811984, 2015). "S100a8 was elevated in both 67NR/4T1.2 and EO771/EO771.LMB tumour comparisons, although differential expression of S100a9 was found only in 4T1.2/67NR." (PMID 25633981, 2015). "Therefore targeting S100A8 could be used to prevent the tumor cell migration and growth." (PMID 25789858, 2015). "In a murine model it has been shown that the inflammatory chemoattractants S100A8 and S100A9 released from primary B16 melanoma tumours pre-condition the lungs, create pre-metastatic niches and attract both tumour and inflammatory cells." (PMID 26082798, 2015). "Recently, we reported that proinflammatory proteins S100A8/A9 via interaction with RAGE enhanced the activation of NK cells, which produce interferon-gamma (IFN-γ), and significantly suppressed tumor growth." (PMID 26625258, 2015). "Compared with a number of other members of the S100 protein family, the expression levels of S100A8 and S100A9 in several types of tumor were significantly different to those in normal samples, but rarely in RCC." (PMID 25673070, 2015). "Proteins S100A8 and S100A9 were upregulated in tumor tissues, which was consistent with that in the serum levels." (PMID 25673070, 2015). "The comparisons of S100A8 and S100A9 genes in normal control and different RCC tumor T stages indicated that with T stage progression, the upregulation of S100A8 and S100A9 genes increased." (PMID 25673070, 2015). "S100A8 and S100A9 also increase the motility of circulating cancer cells by p38 mitogen-activated protein kinase (MAPK)-mediated activation of tumor cell pseudopodia." (PMID 25673070, 2015). "These cytokine signals, leading to the lung-specific up-regulation of S100A8 expression and subsequent enhancement in SAA3 expression, account for lung-specific tumor metastasis." (PMID 25268596, 2014). "S100A8 and S100A9 not only promote the recruitment of CD11b+ myeloid cells but also act as chemoattractants which draw tumour cells to premetastatic sites in the lungs." (PMID 26464846, 2013). "In tumorigenesis, MDSCs are attracted from bone marrow to peripheral blood by inflammatory cytokines (e.g., interleukin-1β, interleukin-6, prostaglandin E2), chemokines, tumour-derived growth factors, and myeloid-related proteins such as S100A9 and S100A8." (PMID 26464846, 2013). "Lastly, S100A8 and S100A9 also play a role in cell proliferation and metastasis of primary tumours into the lung." (PMID 26464846, 2013). "The positive rates of S100A8 and S100A9 in tumor cells were 54.8% and 69.1% in the CRC tissues, compared to 7.1% and 16.7% in the matching distal normal tissues respectively (p<0.001)." (PMID 23637971, 2013). "In human GBM primary tumor parenchyma, S100A8 and S100A9 have been identified with higher levels of S100A9 noted in the tumor regrowth parenchyma of patients that received primary resection plus irradiation compared to primary resection alone." (PMID 22251275, 2012).
tumor (continued). "We propose that S100A8 and S100A9 proteins from either infiltrating inflammatory cells or tumor cells play an important role in the interplay among inflammation, angiogenesis, and tumorigenesis." (PMID 22685372, 2012). "The tumor microenvironment has immune suppressive mediators such as PGE2, TGF-β, IL-10, VEGF, GM-CSF, IL-6, S100A8/A9 and SCF that recruit and/or activate MDSC." (PMID 22815789, 2012). "Factors produced by the primary tumor such as VEGF-A, TNFα, and TGFβ also induce expression of the pro-inflammatory cytokines S100A8 and S100A9 in developing pre-metastatic niches in the lung." (PMID 22699312, 2012). "By using immunostaining the expression of S100A8 and S100A9 are shown in the tumor cells such as U251MG glioma, A-431 epidermoid carcinoma and U-2 OS human osteosarcoma cell lines." (PMID 22489132, 2012). "Recently, the increased S100A8 and S100A9 levels were also detected in various human cancers, presenting abundant expression in neoplastic tumor cells as well as infiltrating immune cells." (PMID 20497537, 2010). "Because S100A8 is the downstream target of IL1B, our results strongly support the potential involvement of IL1B in tumor progression." (PMID 20096140, 2010). "The S100 proteins are almost exclusively present in the tumor extracts, even though some S100 members are expressed at low, or very low levels, for example S100A2, S100A4 and S100A8." (PMID 20815901, 2010). "This scheme reiterates the ability of S100A8 and S100A9 to act as ligands for Ager (advanced glycation end-product receptor), which mediates acute and chronic inflammation, tumor development, and metastasis." (PMID 21318167, 2010). "Tumours also exhibited significantly increased expression of ID1 and profound down-regulation of S100A8, highlighting their potential as therapeutic targets for OS." (PMID 20551950, 2010). "Upregulation of S100A8 and S100A9 in premetastatic lung tissue provide a niche for migration of tumor cells." (PMID 19292913, 2009). "It has been reported that S100A8 and S100A9 levels may be a potential prognosticator of DFS in tumor patients; a high percentage of S100A8 and S100A9 means a low DFS." (PMID 41164825, 2025). "The neutrophil marker, S100A8/A929, exhibited nearly 100% expression in the non-basal layer of the tumor parenchyma in both PPCP and APCP." (PMID 40721446, 2025). "Furthermore, S100A8 and S100A9 were shown to be involved in neutrophil and tumor cell motility as well as tumor cell survival, making them interesting targets for preventing metastasis." (PMID 39653768, 2025). "The rPSL-DIA and biological-rPSL-DIA demonstrated trends similar to biological-library-DIA and library-free DIA, significantly differentiating between noncancerous and tumour tissues for proteins such as S100A8 and ITGB1." (PMID 40348885, 2025). "Compared to APCP, PPCP exhibited significantly lower PD-L1 (an immune checkpoint protein expressed on tumor cells) expression and higher expression levels of CD38 (an immunosuppressive marker), S100A8/A9 (a neutrophil marker), and MPO (myeloperoxidase, a neutrophil marker)." (PMID 40721446, 2025). "The USF2/S100A8 axis, in particular, appears to mediate a crucial link between TGF-β signaling and EMT, while glycosylation-related modulation of adhesion further supports tumor cell dissemination." (PMID 40806457, 2025). "The expression changes of NLRP3 and S100A8 in various solid tumors varied widely, suggesting that NLRP3 and S100A8 had multiple regulatory functions in regulating inflammatory vesicle formation with tumor immune evolution and inflammatory pathways." (PMID 40535567, 2025). "By analyzing untreated surgical tissue samples, we found that S100A8/A9 gene expression primarily reflected tumor cell characteristics rather than immune status." (PMID 40670349, 2025). "In vitro experiments revealed that Bv8, S100A8 and S100A9 could all stimulate tumor cell migration, indicating a direct role for these molecules in both neutrophil and tumor cell migration." (PMID 39653768, 2025).
tumor (continued). "When S100A8 and S100A9 are secreted into the extracellular space, they act as pro-inflammatory danger signals and have been shown to play a pivotal role in tumorigenesis by influencing inflammation, proliferation, invasion, and metastasis of tumor cells." (PMID 40725477, 2025). "In particular, S100A8 and S100A9—two highly homologous proteins that typically dimerize to form calprotectin—regulate multiple processes relevant to tumor biology, including immune response, epithelial–mesenchymal transition (EMT), angiogenesis, and metastasis." (PMID 40924339, 2025). "Meanwhile, S100A8/S100A9 from BC cells binds to receptor for advanced glycation end products on MDSCs and can activate the mitogen-activated protein kinase and nuclear factor kappa-B (NF-κB) signaling pathways in tumor cells to stimulate tumor invasion." (PMID 38404689, 2024). "Furthermore, we assessed the relative mRNA levels of S100A8, S100A9, Nos2, and Arg1 in the tumor tissues." (PMID 38952044, 2024). "Extracellularly, S100A8/S100A9 heterodimer fulfils the characteristics of a DAMP and binding with RAGE, through MAPK pathway, contributes to the viability and migration of tumor cells in a concentration-dependent manner." (PMID 39830522, 2024). "Meanwhile, Western blotting showed us that the markers of EMT and stemness traits were all changed by upregulating S100A8 in HCT8 cells and HT29 cells, which meant that S100A8 overexpression reversed Sec C to promote the stemness features and EMT process of the tumor cells." (PMID 38607060, 2024). "Following their transcription, translation, and secretion, S100A8 and S100A9 might interact with RAGE, resulting in amplified RAGE signaling and increased tumor growth." (PMID 37627239, 2023). "Tumor cells attract these cells to the microenvironment and alter their functions and phenotypes by secreting chemoattractants, such as MIC-1, MCP-1, GM-CSF, S100A8/9 and CCL2, to create an immunosuppressive milieu that aids in evading anti-tumor immunity." (PMID 37234776, 2023). "Finally, xenograft tumor assays were adopted to validate the effects of DACH1 on tumor growth and S100A8/A9 expression." (PMID 38093319, 2023). "Notably, compared with PTTG1 and S100A8, approximately 50% MRS1-tumor cells expressed S100A7, with a 34-fold change than the expression percentage in MRS2-tumor cells." (PMID 37543645, 2023). "In addition to the activated intracellular signaling pathway, S100A8/A9-mediated accumulation of myeloid-derived suppressor cell (MDSC) impaires anti-tumor immune response and promoted tumor progression." (PMID 38093319, 2023). "Furthermore, we also detected high expression of S100A8, PDGF and VEGF in tumor cells after eliminating AREG and bFGF once triggered." (PMID 36639835, 2023). "Subclustering analysis of the tumor, myoepithelial, and macrophage populations identified proliferative (TOP2A +), SCD +, and S100A8+ tumor cells, although these populations were not spatially distinct." (PMID 38114474, 2023). "Although S100A8 is not responsible for stimulating cancer cell proliferation, it plays an important role in tumor cell invasion." (PMID 37124724, 2023). "Through the indirect co-culture of fibroblasts and tumor cells, we demonstrated that the CD74-mediated secretions of S100A8/A9 could induce oncogenic expressions of cytokines in NFs." (PMID 37629174, 2023). "Deletion of S100A8 significantly increased numbers of myeloid-derived suppressor cells in bone marrow and spleen, even when not in specific tumor-bearing microenvironments but the natural state." (PMID 36906583, 2023). "The absence of S100A8 in hematopoietic stem progenitor cells in a specific tumor microenvironment significantly diminished the number of CD8+ T cells and affected the function of CD4+ T cells to some extent, which has some similarity with our results." (PMID 36906583, 2023).
tumor (continued). "It has been reported that S100A8 upregulated PD-L1 in macrophages via a TLR4-dependent pathway, and we previously found that the inhibition of TLR4 by Eritoran increased intratumoral infiltration of CD8+ cells in LLC-tumor-bearing mice." (PMID 36932197, 2023). "Moreover, through the in depth analysis of large publicly available databases, we show that TNBC, unlike Luminal-A and Luminal-B BC subtypes, harbors higher levels of both S100A8 and S100A9 respect to non-tumor breast tissues." (PMID 35655319, 2022). "Targeting S100A8 and S100A9 may help stop tumor cells from migrating to places where they can spread." (PMID 35783639, 2022). "The expression of both Calprotectin subunits S100A8 and S100A9 was examined in clinical PeCa specimens using three TMAs reflecting the tumor center (TMA TC, n = 63), the invasion front (TMA IF, n = 57), and the corresponding lymph node metastases (TMA LM, n = 22)." (PMID 36303837, 2022). "In studies of malignant solid tumors, such as CRC, breast cancer, and prostate cancer, S100A8 and S100A9 levels have been found to be elevated in tumor tissues compared with normal and benign tissues, and their increased expression has been associated with tumor aggressiveness and metastasis." (PMID 36510315, 2022). "We detected a high number of CD15+ infiltrating and tumor-intersecting cells in PeCa specimens but not in adjacent normal foreskin with an overlap of S100A8+S100A9+ and CD15+ immune cells." (PMID 36303837, 2022). "The unique high expression level of S100A8 in the CD14 cell cluster indicates that the CD14 cells may play pro-inflammatory and anti-tumor roles in ccRCC." (PMID 35812372, 2022). "We found that the mRNA levels of S100a8/S100a9 were increased in MTMG tissues at multiple developmental stages and tumor tissues, S100a9 expression was increased dramatically in luminal and stromal subpopulations, and Brca1-MT mammary epithelial cell line (G600)." (PMID 35304461, 2022). "For instance, tumor-derived VEGF-A, TGF-β, and TNF-α may induce S100A8 expression in macrophages and endothelial cells, or monocyte/macrophage-derived factors may stimulate its expression in cancer cells." (PMID 35954190, 2022). "Besides, TANs also promote tumor angiogenesis by releasing the pro-angiogenic factors BV8, S100A8/9, and MMPs that activate VEGFA in the extracellular matrix." (PMID 35585567, 2022). "Moreover, S100A8 and S100A9 neutralizing antibodies have been shown to block the recruitment of both myeloid cells and circulating tumor cells." (PMID 33801279, 2021). "One important impact of S100A8 and S100A9 proteins on leukemic cells is also mediated through their action on the recruitment of myeloid derived suppressor cells (MDSC), which promote tumor progression and establish a favorable pro-tumoral niche." (PMID 33801279, 2021). "Moreover, tumor-derived CCL2, CCL12, CXCL5, S100A8, and S100A9 promote the recruitment of immature myeloid cells to the tumor stroma, facilitating the enrichment of both MDSC subpopulations within the TME." (PMID 33430105, 2021). "Indeed, the expression of proteins S100A8 and S100A9 is up-regulated in several tumor types (breast, prostate, colon, melanoma, etc.)." (PMID 33801279, 2021). "In addition, peptibodies, peptide-Fc fusion proteins that target S100A8 and S100A9, reduce tumor burden in multiple cancer models." (PMID 33801279, 2021). "RAGE is also involved in S100A8/A9-mediated activation of mitogen-activated protein kinase (MAPK) and nuclear factor kappa-light-chain-enhancer of activated B cells (NF-κB) signaling in PC progression, thereby promoting tumor growth, spread, and metastasis." (PMID 34527585, 2021). "Upregulation of S100A8 and S100A9 occurs in various human cancer types and may participate in tumor growth, metastasis, angiogenesis and immune evasion." (PMID 34485305, 2021). "S100A8–RAGE interaction activates p38, ERK, and JNK pathways in tumor cells." (PMID 34575195, 2021).
tumor (continued). "Conversely, low extracellular CLP concentrations finally promote migration of cancer cells and S100A8 and S100A9 expression knockdown and may increase malignancy and tumor invasion." (PMID 33567747, 2021). "Indeed, S100A8 and S100A9 expression was significantly reduced in the presence of anti-TGF-β antibodies in tumor-bearing mouse sera." (PMID 34201758, 2021). "S100A8 and S100A9 expression was found significantly higher in cancer tissues than in para-cancer tissues and correlated with tumor differentiation, which may be a potential marker for poor prognosis in NSCLC." (PMID 33567747, 2021). "Moreover, S100A8 and S100A9 proteins contribute to tumor growth, metastasis development, angiogenesis, and immune escape in a wide variety of solid cancers." (PMID 33801279, 2021). "In LM8-bearing mice, S100A8 expression in the lungs also showed no marked change compared to parental Dunn-bearing mice and tumor-free mice (Figure A3)." (PMID 32325684, 2020). "Finally, as knockdown of S100A8 and S100A9 revealed the most prominent effect on clonogenic growth and cell migration, we tested the in vivo relevance of our findings in tumor xenograft assays." (PMID 32503348, 2020). "Following this unbiased and hypothesis-driven combined approach, we identified S100A8, S100A9, and LGALS3BP as proteins overexpressed in the tumor-initiating cell populations." (PMID 32503348, 2020). "In an 80 μm resolution MALDI MS image series of the 4–17 kDa range of LMW proteins, S100A8 and S100A9 were essentially undetectable in the healthy stromal areas of the specimen, while they were present in the tumor and tumor stroma as well as in the healthy epithelial region." (PMID 32733643, 2020). "S100A8/A9–RAGE interaction has been revealed to stimulate MDSC migration and tumor growth." (PMID 33117687, 2020). "Partially expressed also in the tumor, potential negative tumor markers with a MW of 4615 Da and 15126 Da had little added value to S100A8 and S100A9." (PMID 32733643, 2020). "In multivariate Cox regression analysis of stage IV patients S100A8/A9, LDH, and S100B were independent prognostic factors with S100B as most powerful marker highlighting the extraordinary impact of tumor burden in stage IV disease." (PMID 31806053, 2019). "S100A8 and S100A9 are known to have a dual role in tumor progression." (PMID 30808902, 2019). "Other BAL neutrophil genes, such as IL17, S100a9, S100a8 and Arginase 1 were not statistic altered by the tumor growth." (PMID 31712726, 2019). "We measured the expression of six different Zn-binding proteins in tissue microarrays (TMAs) from OPSCC patients by IHC in matched tumor and normal tissue, including: Lipocalin-1 (n = 63), AZGP1 (n = 68), albumin (n = 26), S100A7 (n = 53), S100A7 (n = 53), S100A8 (n = 51) and S100A9 (n = 50)." (PMID 31740720, 2019). "As opposed to this quantitative character of the tumor burden-correlated biomarkers, S100A8/A9 is likely to reflect the polarization and metastatic potential of the TME." (PMID 31806053, 2019). "The majority of proteins (ACTR2, CSTB, LTA4H, PGK1, NDRG1, FSCN1, ITGAV, THBS2) significantly associated with clinical parameters showed lower expression in the ITF of the tumor stroma or neoplastic islands, with the exception of COL6A1, COL1A2, S100A8, S110A9, and MB." (PMID 30185791, 2018). "Interference with S100A8/A9 signaling inhibits MDSC function, leading to decreased tumor growth." (PMID 30298121, 2018). "Among them, 13 proteins correlated with clinicopathological parameters and of these proteins, eight proteins were identified in neoplastic islands (ACTR2, CSTB, COL1A2, LTA4H, PGK1, NDRG1, S100A8, S100A9) and five proteins were identified in tumor stroma (COL6A1, FSCN1, ITGAV, MB, THBS2)." (PMID 30185791, 2018). "S100A8/A9 homo/heterodimers can interact with the tumor cell surface receptors like RAGE and TLR4 resulting in the activation of MAPK and NF-κB signalling pathways, which promotes tumor growth and invasion." (PMID 29568375, 2018).